ERCC1 (ERCC excision repair 1, endonuclease non-catalytic subunit)
Diseases named in the same sentence as ERCC1 in open-access papers (continued):
Sharing a sentence is not in itself a finding about the gene and the disease.
cancer (continued). "The accumulated case-control results in other types of cancer showed that the genotypes of ERCC1 may also contribute to TNBC, but this has never been investigated." (PMID 30096175, 2018). "Additionally, we provided a set of commercially available compounds, which can potentially bind to the XPF catalytic site and inhibit the endonuclease activity of ERCC1-XPF; therefore, they can be considered in combination with DNA-damaging cancer therapies to amplify their effects." (PMID 29710850, 2018). "Two ERCC1 polymorphisms selected for this study, p.Asn118= (rs11615) in exon 4 and c.1510C>A (rs3212986) in 3’UTR are extensively studied in many cancers and chemotherapeutic regimes because of their negative influence on the stability and level of ERCC1 mRNA and on the protein expression." (PMID 29507678, 2018). "As a result, treatment with ICRF-193 could have an even greater effect on cancer cells which have lost key molecules of the NHEJ pathway, such as 53BP1 or DNAPK, or other important DNA repair factors presented in this study, such as SLX4, and the Ercc1-XPF complex." (PMID 38977669, 2024). "Among the identified polymorphisms of DNA repair genes, excision repair cross-complementing group 1 (ERCC1) and X-ray repair cross complementing group 1 (XRCC1) play an indispensable role in nucleotide excision repair and may be related to the incidence rate of some cancers." (PMID 37400750, 2023). "Residual carcinoma cells exhibit some changes of their features after RFA; however, there is no report about the change of their ERCC1 expression by now." (PMID 24345485, 2013). "ERCC1 plays a crucial role in NER and has been reported to influence the effectiveness of cisplatin-based therapy for gastric and other cancers in a negative manner." (PMID 19875432, 2011). "Overall efforts resulted in several potent ERCC1-XPF endonuclease inhibitors which are capable to diminish NER activity and enhance the cytotoxicity of platinum-based chemotherapeutics although these inhibitors are not explored in targeting DSB repair and its defects for cancer therapy." (PMID 35463312, 2022). "F06 was able to sensitize cancer cell lines to interstrand crosslinking chemotherapeutics; however, reports now suggest this activity is not specific to ERCC1–XPF, and may disrupt the ERCC1–XPA interaction." (PMID 29757235, 2018). "Furthermore, uptake of Tf-cisplatin in cancer cells was not mediated by copper (cisplatin) transporting proteins, which may explain the lack of changes in expression levels of MDR1, ERCC1 and LRP in Tf-cisplatin treated cells compared to controls." (PMID 28484093, 2017).
adenocarcinoma (15 papers, 2011 to 2017). A common cancer characterized by the presence of malignant glandular cells. "Furthermore, EGFR mutations in the adenocarcinoma subgroup were correlated with ERCC1 expression levels (P=0.001)." (PMID 25667646, 2015). "Analysis of these results indicates that ERCC-1 expression was significantly different in the primary lesions and metastatic lymph nodes of patients with adenocarcinoma." (PMID 22890830, 2012). "Our eQTL and survival results indicate that lower ERCC1 expression in non-involved lung tissue of adenocarcinoma patients, in presence of the C allele, was associated with better outcome." (PMID 28181565, 2017). "Similar results were obtained comparing patients with pancreatic body/tale adenocarcinoma with normal levels of ERCC1 to those with higher expression (PFS: 11 vs. 5 months, HR 0.24, 95% CI 0.09-0.62, p< .0001; OS: 14 vs. 8 months; HR 0.25, 95% CI 0.09–0.66, p<.0001; DCR 94% vs. 57%; p= .03)." (PMID 27147577, 2016). "The median OS was significantly better in patients with adenocarcinoma (P = 0.014) and patients who had never smoked (P = 0.040), whereas it was unrelated to other factors such as age, EGFR mutation, and ERCC1." (PMID 23940741, 2013). "Apparently, the expression of these genes did not predict for the outcome of adenocarcinoma patients in our series, in line with recent reports with immunohistochemistry for Ercc1 and Brca1." (PMID 22866924, 2012). "Interestingly, we found significantly different expression of ERCC-1 in the metastatic and primary lesions of NSCLC patients with adenocarcinoma." (PMID 22890830, 2012). "Our results suggest that expression of ERCC-1 was significantly different in primary tumors and metastatic sites of NSCLC patients with adenocarcinoma and that the serum level of CEA was significantly higher in NSCLC patients with adenocarcinoma." (PMID 22890830, 2012).
kidney disease (4 papers, 2013 to 2025). "Here, we compared the glomerular transcriptome of young and aged Ercc1-deficient mice to young and aged WT mice in order to establish a novel model for research of aging-related kidney disease." (PMID 23947592, 2013). "Ercc1 knockout resulted in accumulation of DNA damage and ensuing albuminuria and kidney disease." (PMID 40392611, 2025). "Collectively, these findings highlight the potential of targeting DNA damage pathways, such as via restoring expression of repair factors like KAT5, ATR, FANCD2 and ERCC1 in kidney cells, as a therapeutic approach to slow down the progression of kidney disease in both tubular cells and podocytes." (PMID 38773208, 2024).
genetic diseases (3 papers, 2016 to 2022). "Associations between genetic variation in ERCC1/XPF and several human genetic diseases have been shown in previous research." (PMID 33067872, 2020).
colorectal (2 papers, 2013 to 2025). "Our data show relationships between negative ERCC1 or BRCA1 expression and clinical CRC LNM, implying that both ERCC1 and BRCA1 are involved in CRC metastasis, and that reduced expression of these proteins are early events in colorectal carcinogenesis." (PMID 23496813, 2013). "We found negative expression of ERCC1 to correlate with LNM and advanced TNM stage, implying that ERCC1 decreases CRC metastasis, and by extension, that its reduced expression might be an early event in colorectal carcinogenesis." (PMID 23496813, 2013).
heart disease (2 papers, 2022 to 2023). "Ckmm‐Cre+/−;Ercc1−/fl mice expired suddenly of heart disease by 7 months of age." (PMID 36734200, 2023).
infection (2 papers, 2009 to 2020). The state of being infected such as from the introduction of a foreign agent such as serum, vaccine, antigenic substance or organism. "Concomitant with a decrease in ERCC1 protein levels by both shRNAs, there was a significant increase in the number of SA‐β‐gal‐positive cells and a decline in the number of proliferating (EdU positive) cells 7 days after infection." (PMID 31737985, 2020). "Interestingly, the levels of the ERCC-1 protein seem to be drastically up-regulated during infection in the absence of functional RNAi." (PMID 19220914, 2009).
metabolic disorders (2 papers, 2018 to 2022). "Moreover, it is recognized that deficiency in DNA repair machinery such as ATM, WRN, and Ercc1, accelerates aging and causes severe metabolic disorders." (PMID 29717979, 2018). "Furthermore, the effect of PARP4 and ERCC1 variations on the relation between PMs exposure and glucose level has not yet been reported, although positive associations between DNA damage accumulation and the development of metabolic disorders were reported." (PMID 35627777, 2022).
neurodegenerative disease (1 paper, 2015). A disorder of the central nervous system characterized by gradual and progressive loss of neural tissue and neurologic function. "These genes were grouped according to specificity and association strength 1) to the individual mouse models, 2) to both aging models (physiological aging + Ercc1 accelerated aging), or 3) to both neurodegenerative disease models (App-Ps1 + Sod1)." (PMID 26001565, 2015).
peripheral neuropathy (1 paper, 2013). A disorder affecting the peripheral nervous system. "In the present study, correlations were identified between the polymorphism patterns of TS, MTHFR, ERCC1, ERCC2, GSTP1, GSTT1 and GSTM1 and the clinical outcome, including the incidence of peripheral neuropathy, in Japanese MCRC patients who were treated with modified FOLFOX6 (mFOLFOX6)." (PMID 24137384, 2013).
ERCC1 also shares sentences with these, for which no sentence is quoted: metastatic melanoma (3 papers); renal failure (3); sarcoma (3); cardiovascular diseases (2); endometrial carcinoma (2); glioblastoma (2); hyperlipidemia (2); laryngeal tumors (2); malignant mesothelioma (2); mesothelioma (2); rectal tumors (2); soft tissue sarcoma (2); trichothiodystrophy (2); adrenocortical carcinomas (1); alcohol-dependent (1); Alzheimer disease (1); amyotrophic lateral sclerosis (1); astrocytoma (1); atherosclerosis (1); Azoospermia (1); benign tumor (1); bone tumor (1); brain disease (1); brain ischemia (1); Cachexia (1); cardiomyopathy (1); cholangiocarcinoma (1); Cholestatic liver disease (1); chronic lymphocytic leukaemia (1); cryptorchidism (1).
A further 56 diseases each share a sentence with ERCC1 in 1 paper.